APOBEC3C (apolipoprotein B mRNA editing enzyme catalytic subunit 3C)
Diseases named in the same sentence as APOBEC3C in open-access papers (continued):
Sharing a sentence is not in itself a finding about the gene and the disease.
schizophrenia (1 paper, 2024). A major psychotic disorder characterized by abnormalities in the perception or expression of reality. "TET1 expression was increased, while APOBEC3A and APOBEC3C expression was decreased in the frontal cortex of schizophrenia patients, suggesting that the disruption of the DNA methylation and demethylation pathways may contribute to elevated 5hmC levels in schizophrenia patients." (PMID 38203806, 2024).
cancer (19 papers, 2012 to 2026). A tumor composed of atypical neoplastic, often pleomorphic cells that invade other tissues. "We further analyzed how the genes playing an important role in the development of cancers have an association with Apobec3c, known to inhibit RE expression in cells." (PMID 37352273, 2023). "In this regard, the carcinoma-specific upregulation of APOBEC3B and downregulation of APOBEC3C expression, which were found in our study, can provide strong support for cancer-associated etiology." (PMID 37121965, 2023). "Meanwhile, the loss of active promoter and enhancer signals at the APOBEC3C gene in the ER+ cancer cell reflects the down-regulation of this gene observed in the ER+ subtype." (PMID 26682542, 2015). "Conversely, we found a significantly negative correlation between the total number of C>T/G>A mutations per tumor exome and APOBEC3C mRNA levels in ER− cancers (ρ = −0.26, P = 0.001), which is also supported by the locally weighted regression." (PMID 26682542, 2015). "PCR methods can reliably detect APOBEC3C transcripts in a wide range of human tissues and cancer cell lines, and A3C is often the most abundantly expressed at the mRNA level." (PMID 41501001, 2026). "The TCGA database presents the APOBEC3C protein expression levels in 20 different types of cancer, suggesting that the expression of APOBEC3C in tumor samples is significantly higher than that in normal samples." (PMID 40704619, 2025). "Apolipoprotein B mRNA-editing catalytic polypeptide-like 3C (APOBEC3C), a member of the APOBEC3 subfamily, is implicated in HIV-1 restriction, with an unclear relationship to cancer." (PMID 35601497, 2022). "Relative to ER− cancer cell lines, these results show the down-regulation of both the APOBEC3B and APOBEC3C genes in ER+ cancer cells." (PMID 26682542, 2015). "Among all the APOBECs, APOBEC3C showed the highest expression in pan-cancer." (PMID 35673559, 2022). "Compared with APOBEC3B, the APOBEC3C gene may play a different role in the cancer genome mutagenesis." (PMID 26682542, 2015). "Furthermore, compared with the normal HMECs, the loss of promoter activity at the APOBEC3C, APOBEC3F, and APOBEC3G genes was specifically detected in the ER+ cancer cell." (PMID 26682542, 2015). "Other APOBEC family members have no or very low expression levels in normal or cancer cells with an exception of APOBEC3C, whose expression levels are highest in normal cells and decline slightly in the ER− cancer cell lines, but drop sharply in the ER+ cancer cell lines." (PMID 26682542, 2015). "APOBEC3C is a member of the APOBEC family that plays important but distinct roles in host defense and mediates C-to-T mutagenesis in cancers." (PMID 38022627, 2023). "Indeed, analysis of Cancer Cell Line Encyclopedia confirmed that Ets1 expression was negatively correlated with Dnmt3a (Spearman r = −0.4139, **p = 0.0011) and Dnmt3b (Spearman r = −0.5878, ***p < 0.0001) but positively with Apobec3c (Spearman r = 0.6239, ***p < 0.0001)." (PMID 30467308, 2018). "Such phenomena are consistent with our findings that there is less functional interaction between APOBEC3C and APOBEC3B proteins, suggesting they may perform different roles in cancer cells." (PMID 26682542, 2015). "On the other hand, the substantial up-regulation of APOBEC3B gene and absence of down-regulation of APOBEC3C gene in ER− subtypes suggest that the cytosine deaminase activity for APOBECs may be distinct in cancer subtypes." (PMID 26682542, 2015). "However, the negative correlation for APOBEC3C is not obvious in ER+ cancers." (PMID 26682542, 2015).
cancer (continued). "In contrast, in the ER+ cancer cell line MCF-7, we only observed promoter activity at the APOBEC3B, but not at the APOBEC3C and the other APOBEC family genes." (PMID 26682542, 2015).
tumor (17 papers, 2015 to 2026). "APOBEC3C (A3C) induces genomic instability, accelerating tumor progression; it is associated with immune suppression in the tumor microenvironment." (PMID 41201287, 2025). "High expression of APOBEC3C (A3C) is associated with an immunosuppressive state in the tumor microenvironment, and this molecule accelerates tumor progression by inducing genomic instability." (PMID 41201287, 2025). "Further study showed that the T allele of rs139293 was associated with the altered expression of APOBEC3H and APOBEC3C and that the two genes were co-expressed in both tumor and adjacent normal tissues." (PMID 26459911, 2015). "Genes like APOBEC3B, APOBEC3C, and YTHDC1, highly expressed in tumor cells, were linked to tumor stemness and correlated with markers such as SOX2 and BM1." (PMID 39409886, 2024). "The APOBEC3C mRNA expression level measured by qRT–PCR was cross-validated at protein level by performing IHC in 60 FFPE tumour tissues (FUSCC cohort B1)." (PMID 35750693, 2022). "Whereas, overexpression of APOBEC3C and EIF4E3 in patients were associated with better survival, suggesting their potential role as tumor suppressor genes." (PMID 30881302, 2019). "APOBEC3C mediates tumor immunomodulation and stemness maintenance across various malignancies." (PMID 40307857, 2025). "Here, we unveil that the enhanced expression of the RNA‐binding protein DNA dC → dU‐editing enzyme APOBEC‐3C (APOBEC3C; also known as A3C) in ccRCC tissue and ccRCC‐derived cell lines serves as a catalyst for tumor growth by amplifying nuclear factor‐kappa B (NF‐κB) activity." (PMID 39183666, 2025). "High APOBEC3C expression contributes to tumour plasticity; thus, tumours are able to adapt more easily to evolutionary pressure, such as chemotherapy, and are more prone to developing new phenotypes for recurrence or metastasis, which account for the worse prognosis." (PMID 35750693, 2022). "Finally, we showed that APOBEC3C expression correlated with PDAC tumour microenvironment (TME) remodelling." (PMID 35750693, 2022). "High genomic alterations in zesto lesions were inversely correlated with putative tumor suppressor genes (MTUS2, DLGAP3, RTN1, CRLF1, SLC12A5, and PDIA2) and positively correlated with APOBEC mutagenesis (APOBEC3C, APOBEC3G, APOBEC3B, and APOBEC3F) and hypoxia-related gene signatures." (PMID 40319462, 2025). "Indeed the expression levels of APOBEC1, APOBEC3B, APOBEC3C and APOBEC3F were found to be significantly higher in both primary and metastatic tumours as compared with normal tissues (P<0.01)." (PMID 26647728, 2015).
infection (6 papers, 2007 to 2023). The state of being infected such as from the introduction of a foreign agent such as serum, vaccine, antigenic substance or organism. "The temporal pattern of UNG depletion was distinct from that of other accessory protein substrates, including APOBEC3C, with degradation seen as early as 6 hr post-infection, and preserved in the presence of reverse transcriptase inhibitors." (PMID 27690223, 2016). "Accordingly, cell surface proteins targeted specifically by Vpu (tetherin and SNAT1) are depleted late in the time course of infection, and intracellular proteins known to be targeted by Vif (APOBEC3C) and Vpr (UNG) show distinct temporal profiles." (PMID 27690223, 2016). "However, the fact that APOBEC3C is antagonized by Vif does suggest that APOBEC3C is an important barrier that must be countered by the virus during natural infections." (PMID 27732658, 2016). "APOBEC3C and APOBEC3G levels were higher in MCPyV+ MCCs compared with MCPyV− MCCs, and APOBEC3G showed statistically significant coexpression with LT, which could implicate an immune response to MCPyV infection and make APOBEC3C and APOBEC3G potential LT mutators." (PMID 36970060, 2022). "HIV-1 and HIV-2 Vif are able to antagonize both variants of APOBEC3C so the I188 SNP may not block HIV transmission, so Vif may effectively counteract I188 activity during infection." (PMID 27732658, 2016).
APOBEC3C also shares sentences with these, for which no sentence is quoted: hepatocellular carcinoma (2 papers); pancreatic ductal adenocarcinoma (2); anaplastic oligodendroglioma (1); breast tumors (1); Cirrhosis (1); colorectal tumors (1); head and neck cancer (1); lung adenocarcinoma (1); myeloproliferative neoplasm (1); pancreatic cancer (1); prostate adenocarcinoma (1); rectum adenocarcinoma (1); renal carcinoma (1); stomach cancer (1); uterine corpus endometrial carcinoma (1).